MGMT (O-6-methylguanine-DNA methyltransferase)
Diseases named in the same sentence as MGMT in open-access papers (continued):
Sharing a sentence is not in itself a finding about the gene and the disease.
tumor (continued). "Furthermore, α-syn lowers MGMT and cyclin D1 (CCDN1) expressions and reduces tumor development in allografted mice." (PMID 40108111, 2025). "While MGMT represents an important component of tumour cell resistance against TMZ, other tumour‐inherent factors play critical roles as well, both in human and canine tumours." (PMID 40377133, 2025). "First, this study did not directly investigate TMZ resistance mechanisms, such as MGMT expression, DNA repair pathways, or tumor heterogeneity, which are critical factors influencing TMZ effectiveness." (PMID 40855299, 2025). "A meta-analysis found that MGMT-methylated tumors typically exhibit less aggressive MRI features on conventional MRI, such as reduced peritumoral edema and tumor burden, compared to non-methylated." (PMID 41476598, 2025). "Furthermore, we have observed a notable distinction between MGMT methylated, MGMT(−), and MGMT unmethylated, MGM(+), patient tumours in terms of the wavelet_GLCM_Imc2 feature." (PMID 40282434, 2025). "While indisulam monotherapy has shown limited anti-tumor activity, albeit with acceptable toxicity, combining RBM39 degraders with MGMT inhibitors such as O6-BG could yield synergistic suppression of MGMT with reduced toxicity." (PMID 41300971, 2025). "The rationale for temozolomide is the expected clinically significant survival improvement for 30–40% of patients with MGMT-methylated tumours, the lack of better alternatives for unmethylated tumours, and its relative safety and tolerability." (PMID 39099691, 2024). "1p/19q-codeletion and MGMT methylation did not have a significant impact on the perfusion in tumor and edema." (PMID 39036439, 2024). "Riluzole was found to enhance the anti-tumor activities of temozolomide in MGMT-positive but not MGMT-negative GBM cell lines." (PMID 38672652, 2024). "Patients who are more likely to tolerate CWI at reresection typically have a non-altered preoperative general status (KPS > 80%), no preoperative neurological deficit, a tumor displaying a highly methylated MGMT promotor, and are amenable to GTR." (PMID 39456559, 2024). "The tumor was IDH wild-type and the MGMT promoter region was unmethylated." (PMID 38837109, 2024). "MGMT is a DNA repair enzyme that antagonizes the alkylating effect of the alkylating agent TMZ on the O6 guanine group, reducing the cytotoxic effect of the tumor cells and rendering the cells resistant to the drug." (PMID 38992201, 2024). "There was also a trend for longer OS of patients with an MGMT promoter-methylated tumor; however, this was not statistically significant (P = .137, HR 0.64, CI 0.36–1.15)." (PMID 38496908, 2024). "Younger age, a better clinical status at diagnosis, tumor location outside of eloquent regions, gross total resection (GTR) of the tumor, and promotor methylation of the O-6-methylguanine-DNA methyltransferase (MGMT) count to the most relevant prognostic factors in GBM patients." (PMID 38639854, 2024). "In cases where patients have tumours with MGMT methylated, temozolomide rather than radiation is recommended." (PMID 39099691, 2024). "Drug resistance almost always rapidly develops to TMZ, however, either from high expression of the repair protein O6-methylguanine-DNA methyltransferase (MGMT) or resulting from TMZ-induced damage to the MMR pathway, preventing the futile cycling that leads to tumour cell apoptosis." (PMID 39048947, 2024). "MGMT promoter methylation silences the gene, MGMT protein is not expressed, and the tumours are more sensitive to TMZ treatment." (PMID 39516685, 2024).
tumor (continued). "The significantly lower proportion of MGMT promoter methylation in GC patients warrants further investigation, and the possibility of lower tumor purity in GC patients contributing to a false negative result in MGMT promoter methylation should be considered." (PMID 39127694, 2024). "Patients with SVZ + assigned tumors showed larger contrast-enhancing tumor volume (median 51.8 vs. 5.5 cm3) and a higher fraction of Karnofsky performance status (KPS) < 80% (n = 7, 24.1% vs n = 3, 12.0%), MGMT promoter methylation was less common (n = 9, 31.0% vs. n = 13, 52.0%)." (PMID 38376766, 2024). "Improved overall survival was seen with methylated MGMT (HR = 0.38, 95% CI 0.26–0.56, p ≤ 0.001) and non-measurable contrast-enhancing residual tumour (compared with biopsy) (HR = 0.53, 95% CI 0.32–0.87, p = 0.01)." (PMID 38744979, 2024). "MGMT inhibitors, despite promising preclinical results, have not exhibited significant benefits in clinical settings for tumor patients treated with alkylating agents." (PMID 38254819, 2024). "A Phase III trial implemented dose-dense TMZ, aiming to deplete MGMT in tumor cells, but failed to improve TMZ sensitivity." (PMID 38224404, 2024). "Therefore, we explored the tumor malignant phenotypes influenced by the up‐regulation of MGMT expression in relatively low‐MGMT cell lines (MIN6 and Bon‐1) and the downregulation of MGMT expression in relatively high‐MGMT cell lines (QGP‐1 and SPNE1)." (PMID 39041891, 2024). "The tumor exhibited no IDH1, IDH2, TERT, H3, or BRAF mutation, and had no EGFR amplification, no MYB rearrangement, and a positive MGMT status." (PMID 39227460, 2024). "Thus, hypermethylation of the MGMT gene promoter can confer a greater sensitivity of the tumor cell to pharmacological treatment with TMZ, and the MGMT promoter methylation status is currently used as a predictor for the benefit of TMZ therapy." (PMID 39408901, 2024). "Variables associated with statistically significant effects on PFS or OS (MGMT promotor methylation, EOR, Stupp therapy, radiation therapy, bi-hemispheric involvement) and established variables (age, KPS, tumor volume) were included in a multivariate survival analysis." (PMID 39560695, 2024). "The six-month progression-free survival was significantly higher in patients with MGMT-methylated tumours compared to those with unmethylated tumours, regardless of the dosing regimen." (PMID 39099691, 2024). "Tumours with an unmethylated MGMT promoter region, where MGMT is active, have brisk DNA repair mechanisms and are less sensitive to cytotoxic treatment with temozolomide (TMZ), which remains the most effective drug in this tumour." (PMID 39148319, 2024). "For the 18 total cases with tumor molecular data available, MGMT promoter methylation was absent in 15 (83%)." (PMID 38968484, 2024). "Three patients had an insufficient tumor cell percentage in the sample (< 20%), and one patient was diagnosed at another hospital, so the tumor was not available to perform MGMT studies." (PMID 38762534, 2024). "MGMT expression by multiplex QIF revealed prominent tumor MGMT protein from 6/9 patients without benefit, while MGMT protein was lower in 3/9 with benefit." (PMID 37387791, 2023). "Unfortunately, the study did not include tumor volumes or the methylation status of the MGMT promoter region." (PMID 37289281, 2023). "Meanwhile, work from UCSF has demonstrated that temozolomide positively selects for tumor cells with MGMT hypermethylation in patients with LGGs lacking DNA mismatch repair (MMR)." (PMID 36831683, 2023). "Our results showed that all three monocyte subpopulations presented higher expression of IL-10 from patients without MGMT methylation in tumor cells." (PMID 36768201, 2023). "Irrespective of the poor prognosis of GB patients, the tumor’s MGMT promoter methylation status, which can be found by radiogenomic classification of mpMRI scans, is extremely important to indicate the chemotherapy response prediction." (PMID 36841898, 2023).
tumor (continued). "On the other hand, in the MGMT-negative group, the tumor diameter was 42.1 mm, which was significantly larger compared with the MGMT-positive group." (PMID 37161026, 2023). "However, in the case of MGMT promoter-methylated GBMs, TMZ is in principle able to control tumor progression and is indeed beneficial for some patients, but still, several GBM cells are able to survive." (PMID 37240419, 2023). "Although we are not aware of data on the amount of O6MeG in the tumor tissue after TMZ treatment, it is reasonable to assume that O6MeG also accumulates in the MGMT-lacking tumor, leading to additive effects even when a low-dose (metronomic) schedule is used." (PMID 38068493, 2023). "In summary, our data underlines the necessity of obtaining tissue and determining MGMT status in the elderly through biopsy if tumor resection is not safely feasible." (PMID 37289281, 2023). "Moreover, low expression of TSPAN7 was highly expressed in IDH wildtype, MGMT unmethylated and MES-like tumor." (PMID 36845098, 2023). "Clinical genomic profiling reported that the MGMT promoter was no longer methylated in the post-treatment tumor, suggesting development of a possible resistance mechanism." (PMID 37192626, 2023). "In MGMT-lacking tumor cells (promoter-methylated), the critical adduct O6MeG is expected to accumulate following repeated treatments, as it is not repaired." (PMID 38068493, 2023). "Tumor characteristics including IDH mutation status and MGMT methylation status were not significantly different between eras." (PMID 36975447, 2023). "MMR protein expression in tumor cells was present with a score of 2 to 3, independent of MGMT status (promoter methylation and protein expression), sex, age, IDH1 mutation status or treatment." (PMID 37047153, 2023). "MGMT and DNMT1 silencing efficiencies in solid tumors by 5-Aza and Lomeguatrib, respectively, were confirmed by Western blot and qRT-PCR with protein and mRNA extracted from tumor tissues." (PMID 37894860, 2023). "It is not excluded that the relative amount of MGMT promoter-unmethylated subclones from the tumor at certain time points become more reflected within the CCCs." (PMID 36831536, 2023). "The MGMT status was available for 64 of the 66 GSC cultures and compared to the parental tumours." (PMID 37620410, 2023). "Factors associated with LM relapse were age less than 50 years (p < 0.01), initial disease located in the temporal lobe (p < 0.01) and tumours lacking MGMT promoter methylation (p < 0.01)." (PMID 37715122, 2023). "We found the association between MGMT promoter methylation status and LMD was strong, no patient with a tumour known to be MGMT methylated had LMD relapse in our study." (PMID 37715122, 2023). "Pt derivatives may also modulate anti-tumour immunity, impair tumour invasiveness through matrix metalloproteinase (MMP) downregulation, exhibit anti-angiogenic effects, and modulate MGMT DNA repair enzyme, among others." (PMID 37242036, 2023). "Recent research demonstrated that MGMT methylation, regardless of tumor grade, is a reliable indicator of chemotherapy efficacy in patients with wild‐type IDH." (PMID 37675821, 2023). "This outcome might be due to a partial escape of the epigenetic silencing of the MGMT protein and an efficient DNA repair via the functional MMR or other DDR systems, such as BER, in the TMZ-treated tumor cells." (PMID 37047153, 2023). "The tumor was still IDH1 wild-type and MGMT promoter-unmethylated." (PMID 36831536, 2023). "All of these patients were older (mean 72.3 years, standard deviation 7.1) and had a tumor lacking O6-methylguanine-DNA methyltransferase (MGMT) promoter methylation." (PMID 36724187, 2023).
tumor (continued). "We were unable to determine the MGMT status of the tumor samples, since it was not routinely assessed in our clinical practice, nor did we have the true extent of the resection reliably available for the whole study population." (PMID 38239655, 2023). "Tumor heterogenity and low material quantity can render MGMT status analysis difficult (even non-representative), when working only on a biopsy." (PMID 37190181, 2023). "Although many studies have been conducted concerning the correlation of visual parameters (tumor location and laterality, enhancement characteristics such as ring enhancement) and MGMT methylation status, there is still no broadly accepted consensus." (PMID 36900177, 2023). "Tumor cells lacking MGMT expression are frequently sensitive to TMZ, whereas MGMT-expressing tumors are commonly resistant to alkylating agents, including TMZ." (PMID 38136323, 2023). "The results reflected that PDCL3 not only revealed satisfactory prognostic efficiency, similar to age, tumor grade, IDH status, 1p19q codeletion and MGMT promoter unmethylated status, but was also an independent predictor in the multivariate Cox regression analysis." (PMID 37006287, 2023). "The majority of tumours were IDH wild type (74.7%) and MGMT promoter unmethylated (43.7%), whereas 17.3% had unknown IDH status and 17.1% had unknown MGMT promoter methylation status." (PMID 36730349, 2023). "Patients with unmethylated MGMT promoter (MGMTneg) did not benefit from tumor-specific therapy (3.6 vs. 3.7 months, p = 0.18)." (PMID 37289281, 2023). "All other tumor locations, age, sex, MGMT methylation status, tumor volume, and edema did not yield a significant regression coefficient B in the analysis (p > 0.05)." (PMID 38063340, 2023). "The mean ADC values in the enhancing tumor region of patients with a negative MGMT methylation status were 0.76×10−3 mm2/s, and in patients with a positive MGMT methylation status, it was 0.79×10−3 mm2/s." (PMID 36900177, 2023). "In the multivariate analysis, the influence of the other parameters (age, sex, edema, tumor volume, all other tumor locations, and MGMT methylation status) studied was not significant." (PMID 38063340, 2023). "When combining VPA and non-VPA cohorts on Cox regression analysis age, RPA, MGMT status, GTV T1, cortical vs. periventricular location, either hemisphere vs. bilateral disease, tumor location, and the administration of VPA were statistically significant for OS." (PMID 37892181, 2023). "For each patient, three assays had to be performed: one on the tested tumor sample, one on a non-neoplastic sample, and one on a positive control (a known MGMT-methylated sample)." (PMID 36826067, 2023). "In this study, we demonstrated that the tumor grade was significantly higher in MGMT-negative tumors (p < 0.001)." (PMID 37161026, 2023). "MGMT promoter methylation status, followed by non-central tumor location and CRET, were the strongest prognostic factors for survival in this population-based study of patients with GBM." (PMID 37711136, 2023). "To be more selective with the tumor model, we screened GSCs with a very low level of methylation of the MGMT promoter (about 4%), known to be a negative prognostic factor for patients diagnosed with GBM." (PMID 38203299, 2023). "Among twenty-one patients with baseline tumor volume ≤32 cm3, ten (47.6%) had MGMT methylation, and eleven had no methylation." (PMID 36009577, 2022). "In this paper, we propose a DL-based approach for MGMT promoter methylation identification leveraging medical knowledge to deal with the lack of tumor segmentation masks." (PMID 36547486, 2022). "However, subsequent validation is still required for MGMT and HIF-1α due to the weak expression in all tumor lesions." (PMID 36591483, 2022). "Conversely, in patients with MGMT unmethylated tumours, there was a non-significant trend favouring the radio-chemotherapy group (median overall survival being 10.0 vs. 7.9 months; HR = 0.75; p = 0.055)." (PMID 35327445, 2022).
tumor (continued). "The authors showed that, for patients with rGB after a treatment-free interval of at least five months, median OS2 and PFS2 were longer for the TMZ rechallenge group than for the nitrosourea group, regardless of the MGMT methylation status of the tumor." (PMID 36428604, 2022). "Cox multivariate analysis including age and MGMT status as covariates showed comparable lack of significance between all enhancing tumor volume measurements and PFS, OS, and PPS." (PMID 36053452, 2022). "MGMT-methylated and unmethylated tumors did not significantly differ in terms of survival in patients with tumor volumes greater than 32 cm3." (PMID 36009577, 2022). "Besides, the clinicopathological features, including tumor grade, histology diagnosis, IDH status, 1p/19q codeletion, TERT promoter status, ATRX status, and MGMT promoter status, were also integrated." (PMID 36467068, 2022). "In our previous work, we showed that α5 integrin expression in primary tumours was not impacted by their MGMT status." (PMID 35053532, 2022). "Several similar attributes have previously been reported, such as texture features in the whole tumor, and studies have specifically found that a GLSZM of low grey-level emphasis could delineate the MGMT status with an AUC of 0.71." (PMID 35743511, 2022). "Several patients presented with complete responses, although it was also recognized that the best response to TMZ is dependent on low, or absent, expression of MGMT in patients’ tumor cells." (PMID 36551551, 2022). "This particularly includes HGG patients at first recurrence with a non-methylated MGMT promotor and tumor progression during the treatment with alkylating agents, but also HGG patients with second or later recurrence." (PMID 35158809, 2022). "In contrast, the recent guidelines of the European Association of Neurooncology do not recommend re-evaluating MGMT at tumor recurrence." (PMID 35563629, 2022). "These constructs exhibited an increased expression of markers of tumor invasion and drug resistance (matrix metalloproteinase-2 and -9 [MMP2, MMP9], vascular endothelial growth factor receptor-2 [VEGFR2], and O6-methylguanine-DNA methyltransferase [MGMT]) when compared to solely U118-printed fibers." (PMID 35804898, 2022). "Several studies, including ours, have highlighted the fact that the average preoperative tumor volume is not a predictive factor of mortality; it correlates with age, symptoms, or the methylation status of the MGMT promoter." (PMID 36547116, 2022). "Furthermore, MGMT methylation analysis revealed MGMT methylation discordance between the core (c) and peripheral (p) portions of samples GB3, GB4, GB6, and GB7, highlighting intra-tumor heterogeneity." (PMID 36132155, 2022). "Currently, there is no direct method to determine the enzymatic activity of MGMT in tumor samples, which is the reason why the MGMT promoter methylation serves as an indirect tool." (PMID 35180887, 2022). "The expression of stem-cell markers was independent of the original MGMT-status or of the growth pattern in monolayers or tumor spheres." (PMID 35563629, 2022). "Patients’ frailty is a key factor negatively influencing survival, alongside with older age, less extensive tumor resection, corticosteroid treatment at baseline and the absence of promotor methylation of the O6-methylguanine-DNA methyltransferase (MGMT) gene." (PMID 36394717, 2022). "The age, gender, tumor volume, extent of resection, and MGMT promoter methylation status were not significantly different between the two groups." (PMID 36294373, 2022). "MGMT promoter methylation (no O-6-methylguanine-DNA methyltransferase enzyme activity) reduces the ability of tumor cells to repair damaged DNA sites after exposure to alkylating agent chemopreparations." (PMID 36289655, 2022). "Tumor treating fields (TTF) is an external device that can eliminate tumors regardless of the MGMT methylation status." (PMID 34976195, 2022).